CTLA4 (cytotoxic T-lymphocyte associated protein 4)
Diseases named in the same sentence as CTLA4 in open-access papers (continued):
Sharing a sentence is not in itself a finding about the gene and the disease.
cancer (continued). "Immunotherapy targeting immunological checkpoints, such as programmed cell death 1 (PD-1), programmed cell death 1 ligand 1 (PD-L1), and cytotoxic T lymphocyte-associated antigen-4 (CTLA-4), has been used as a potential therapeutic strategy for cancers." (PMID 35148766, 2022). "The search criteria for cancer susceptibility associated with the polymorphism in the CTLA-4 gene rs231775 resulted in 87 case-control studies with 29,464 cases and 35,858 controls." (PMID 35600409, 2022). "In particular, programmed cell death protein-1 (PD-1) and cytotoxic T lymphocyte–associated antigen-4 (CTLA-4) are checkpoints which downregulate T cell activation, produced by cancer cells in order to escape from immunity system, producing immune tolerance." (PMID 35742834, 2022). "In contrast, humans or mice that lack PD-1 or cytotoxic T lymphocyte-associated antigen 4 (CTLA-4) exhibit a global autoimmune diathesis that corresponds to the toxicities observed when these structures are targeted in immunotherapy of cancer." (PMID 36275816, 2022). "The meta-analysis in the current study suggests a significant association between CTLA-4 rs231775 polymorphism and some types of cancer and overall risk for cancer." (PMID 35600409, 2022). "We also found differences in cancer-associated fibroblast and macrophage M2 infiltration and the expression of PD-L1, CTLA4, LAG3, and HLA were also observed between the two risk groups (P < 0.05)." (PMID 35144613, 2022). "Pioneering success of antibodies targeting immune checkpoints such as programmed cell death protein 1 (PD-1) and cytotoxic T-lymphocyte-associated protein 4 (CTLA-4) has changed the outlook of cancer therapy." (PMID 35585982, 2022). "The most commonly observed targets on activated T cells and the most reliable for cancer treatment are cytotoxic T-lymphocyte associated protein 4 (CTLA-4), programmed cell death protein 1 (PD-1) and its PD- ligand." (PMID 36614041, 2022). "Future research should provide a more comprehensive clarity of the association between the CTLA-4 rs231775 polymorphism and the risk of developing cancer." (PMID 35600409, 2022). "Meanwhile, we also found that the expression levels of PD-1, PD-L1 and CTLA4 were positively associated with STC2 expression in most cancer types." (PMID 36685853, 2022). "Programmed cell death protein-1 (PD-1) and cytotoxic T-lymphocyte-associated protein-4 (CTLA-4) are examples of immune checkpoints that have been studied extensively in cancer treatment." (PMID 36358744, 2022). "Based on 87 case-control studies, we carried out a meta-analysis, which showed CTLA-4 rs231775 polymorphism plays an important role in cancer risks." (PMID 35600409, 2022). "Among the inhibitory checkpoints, cytotoxic T-lymphocyte-associated protein 4 (CTLA-4) and programmed cell death protein 1 (PD-1) expressed by T cells are the most studied and are promising targets for cancer immunotherapy." (PMID 35008422, 2022). "Programmed death 1 (PD-1) and cytotoxic T-lymphocyte-associated antigen 4 (CTLA-4) are immune check points that negatively regulate T-cell immune function allowing the cancer cells to escape the host immune surveillance." (PMID 35662745, 2022). "CD274, PDCD1, and CTLA-4 were known as critical immune checkpoints that are associated with immune escape in cancers." (PMID 36254230, 2022). "Clinical immune markers, such as PD-1, CTLA-4 and PD-L1, have been confirmed to be closely associated with Ring finger family in a variety of cancers." (PMID 36059474, 2022). "Cytotoxic T-lymphocyte associated protein 4 (CTLA-4) can affect the treatment of advanced cancer and targeting drugs have been used for treating different types of cancer." (PMID 36712869, 2022).
cancer (continued). "For example, blocking the cytotoxic T-lymphocyte-associated antigen 4 (CTLA-4) and programmed death 1 (PD-1) signaling pathways has remarkably improved the effectiveness of immunotherapy against many cancer types." (PMID 36428755, 2022). "Cytotoxic T-lymphocyte-associated protein 4 (CTLA-4) is another crucial molecule involved in immune regulation in cancer." (PMID 35454762, 2022). "Immunotherapy targeting immune checkpoints such as PD-1 (programmed cell death 1) or CTLA-4 (cytotoxic T lymphocyte-associated protein 4) is a real revolution in the treatment of many cancers." (PMID 35406498, 2022). "In recent years, immune checkpoints (ICIs) targeting programmed death 1 (PD1) and cytotoxic T lymphocyte-associated antigen 4 (CTLA-4) have transformed the treatment landscape for various cancers, including CRC." (PMID 36375474, 2022). "The application of anti-programmed cell death protein 1 (PD-1) and anti-cytotoxic T-lymphocyte-associated protein 4 (CTLA-4) agents has greatly benefited cancer patients and achieved satisfactory outcomes in clinical practice." (PMID 36612106, 2022). "Immune checkpoints, including PD-1/PD-L1 and CTLA-4, have gained attention in cancer-associated therapy via immune surveillance and escape." (PMID 36246623, 2022). "Blocking a variety of ICIs, such as PD-1 (programmed cell death-1), programmed cell death-ligand 1 (PD-L1), and cytotoxic T-lymphocyte-associated protein 4 (CTLA-4) has improved the immune system’s efficacy in combating cancer cells." (PMID 35337133, 2022). "In contrast, another study demonstrated that high plasma SCFA levels were associated with shorter PFS in cancer patients treated with CTLA-4 inhibitors." (PMID 36358789, 2022). "Multiple ICIs were approved for cancer therapy such as nivolumab, pembrolizumab, and cemiplimab targeting programmed death-1 (PD-1) and ipilimumab targeting cytotoxic T-lymphocyte-associated protein 4 (CTLA-4)." (PMID 35493471, 2022). "Characteristics of studies of the CTLA-4 gene rs231775 A/G polymorphism and cancer risk included in our meta-analysis." (PMID 35600409, 2022). "This immunosuppressive subset of CD4+ cells has recently been associated with resistance to treatment with novel cancer immunotherapies such as anti-CTLA-4 and anti-PD-1." (PMID 35714487, 2022). "Blockade of immune checkpoints, such as cytotoxic T-lymphocyte associated protein 4 (CTLA-4) and programmed cell death protein-1 (PD-1), has made a great contribution in the immunotherapy of various cancers in recent years." (PMID 35401558, 2022). "The advent of the cancer immunotherapy era brought by approval of therapy antagonizing the immune checkpoint cytotoxic T-lymphocyte-associated protein-4 (CTLA-4) revolutionized the outlook on cancer therapy." (PMID 35304456, 2022). "During HPV infection, increased expression of programmed death-ligand-1 (PD-L1) and cytotoxic T-lymphocyte-associated protein-4 (CTLA-4) on the surface of cancer cells leads to escape from the immune system and the progression of malignancy." (PMID 36276117, 2022). "The cytotoxic T-lymphocyte associated protein 4 (CTLA4) gene encodes a protein that transmits an inhibitory signal to T cells, and plays an important role in increasing cancer susceptibility." (PMID 35860595, 2022). "Our present study indicates that the CTLA-4 rs231775 polymorphism contributes to cancer development and aggression." (PMID 35600409, 2022). "In a similar manner, CTL-associated antigen-4 (CTLA-4) on the surface of cancer cells can interact with CD80/CD86 costimulatory molecules on T cells, thereby blocking full T cell receptor activation by foreign antigen." (PMID 35632572, 2022). "Despite that, genetic diagnosis of particular disorders, which associate with a higher cancer risk, such as NF-κB1 defect or CTLA-4 insufficiency, should urge treating physicians to consider regular cancer screening." (PMID 35250968, 2022).
cancer (continued). "Gut microbes facilitating cancer treatment also extended to the targeted immunotherapies, such as cytotoxic T-lymphocyte-associated protein 4 (CTLA-4) and anti-programmed cell death ligand 1 (anti-PD-L1) therapies." (PMID 36192796, 2022). "As a promising strategy, ICI therapies that block PD-1 or T-lymphocyte-associated antigen 4 (CTLA-4) signaling are being rapidly developed for cancer treatment and showed superior efficacy for intermediate- and poor-risk RCC." (PMID 35205613, 2022). "Recently, the combination of nivolumab and ipilimumab (Nivo/Ipi), an anti-cytotoxic T-lymphocyte-associated protein 4 inhibitor, became available for the treatment of various carcinomas." (PMID 36276492, 2022). "The primary intra-cellular checkpoint proteins that play a major role in cancer pathogenesis and division are the cytotoxic T-lymphocyte-associated antigen 4 (CTLA-4), and programmed cell death-1 (PD-1) checkpoints." (PMID 34221257, 2021). "Several studies have proved the association between programmed death-1 (PD-1) or cytotoxic T-lymphocyte associated antigen 4 (CTLA-4) polymorphisms and the immune escape of cancer." (PMID 33588380, 2021). "In advanced cancer, various immune checkpoint inhibitors, including programmed cell death 1 (PD-1), its ligand PD-L1, and cytotoxic T-lymphocyte-associated antigen 4 (CTLA-4), have achieved promising oncological improvements." (PMID 34069461, 2021). "ICI therapies targeting programmed death 1 (PD-1), programmed death ligand 1 (PD-L1), or cytotoxic T lymphocyte-associated antigen 4 (CTLA-4) have effectively treated various types of cancer." (PMID 33717139, 2021). "Among them, the cytotoxic T lymphocyte-associated protein 4 (CTLA-4), programmed cell death 1 (PD-1), and PD-1 ligand (PD-L1) received great attention in recent years due to their use in cancer therapy." (PMID 34658896, 2021). "Previous studies have shown that the cytotoxic T lymphocyte associated protein-4 (CTLA-4) and programmed cell death protein-1 (PD-1) play an essential role in the development of cancer immunotherapy." (PMID 34576068, 2021). "Ipilimumab (Yervoy) is a CTLA-4-associated monoclonal antibody (mAbs) that improves the body’s immune response to cancer cells." (PMID 33401586, 2021). "CTLA-4 (cytotoxic T-lymphocyte-associated protein 4) was originally defined as a T-lymphocyte antigen and was used as a target in cancer immunotherapy." (PMID 33925389, 2021). "The effect of rapamycin on the efficacy of anti-cancer vaccination was also tested in combination with cytotoxic T-lymphocytes-associated protein 4 CTLA-4 blockade." (PMID 33802831, 2021). "In patients with other cancers, GI AEs are more likely with regimens containing an anti- cytotoxic T-lymphocyte-associated protein 4 (CTLA4) agent and less likely with anti-PD-1 or -PD-L1 monotherapy." (PMID 34377156, 2021). "Blockade of classical CTLA-4 (cytotoxic T lymphocyte-associated antigen-4) and PD-1 (programmed cell death protein-1) checkpoint pathways have become the cornerstone of anti-cancer immunotherapy." (PMID 34531847, 2021). "Over the past decade, immune checkpoint inhibitors (ICIs), including antibodies against the programmed death 1 (PD-1) receptor, its ligand (PD-L1), and cytotoxic T-lymphocyte-associated protein 4 (CTLA-4), have become a mainstay of treatment against cancer." (PMID 33806963, 2021). "Immune checkpoint blockade targeting programmed death 1 (PD-1)/programmed death ligand 1 (PD-L1) and cytotoxic T lymphocyte-associated protein 4 (CTLA-4) has become a promising approach for anti-cancer immunotherapy." (PMID 33816277, 2021). "Although patients with germline CTLA4 gene variants and response of cancer patients to ICI therapy are fundamentally very different, both result in an impairment of CTLA-4 binding, impacting the function of Tregs." (PMID 34777387, 2021).
cancer (continued). "Inhibitors and vaccines targeting classical immune checkpoint molecules in the TME, such as programmed cell death-1 (PD-1) and cytotoxic T-lymphocyte-associated antigen 4 (CTLA-4), have achieved remarkable progress in several types of cancers." (PMID 35223862, 2021). "Immune checkpoint blockade (ICB) in cancer immunotherapy aids the immune system in recognizing and killing cancer cells by targeting the cytotoxic T-lymphocyte-associated protein 4 (CTLA4), programmed death 1 (PD1), and programmed death-ligand 1 (PD-L1)." (PMID 34439277, 2021). "Among the different checkpoints expressed by cancer cells, cytotoxic T-lymphocyte-associated protein 4 (CTLA-4) and PD-1 are the most explored checkpoints for ICI-based therapeutics." (PMID 34371708, 2021). "Over the past decade, researchers have used blocking antibodies to programmed cell death 1 (PD-1) and cytotoxic T-lymphocyte-associated protein-4 (CTLA-4) to reactivate the immune system and eliminate cancer cells." (PMID 34745124, 2021). "Cancer immunotherapy has been greatly improved and promoted by pharmacological blockage of so-called immune checkpoint receptors such as CTLA-4 (cytotoxic T-lymphocyte-associated protein 4), PD-1 (programmed cell death protein 1), and its ligand PD-L1." (PMID 34006895, 2021). "Compared with epithelial cancer cells, mesenchymal cancer cells are less responsive to anti‐cytotoxic lymphocyte‐associated protein 4 (CTLA4) immunotherapy." (PMID 34977870, 2021). "Recently, therapies using immune checkpoint inhibitors, such as anti-cytotoxic T lymphocyte-associated antigen 4 (anti-CTLA-4), and the anti-programmed cell death protein 1 pathway (anti-PD-1/PD-L1) have performed well in the treatment of cancers." (PMID 33597971, 2021). "To date, 6 anti–programmed death receptor-1/programmed death receptor-ligand 1 (anti–PD-1/PD-L1) agents and 1 anti–cytotoxic T-lymphocyte-associated protein 4 (anti–CTLA-4) agent are approved for a variety of cancers." (PMID 34375311, 2021). "Among the cancer susceptibility studies, CTLA-4 +49 A/G polymorphism is the most widely studied mutation point." (PMID 33819967, 2021). "Future more large-scale and well-designed studies with functional evaluations should be carried out to definite the results and investigate the molecular mechanisms of CTLA-4 modify cancer risk." (PMID 33819967, 2021). "Some studies have shown that CTLA-4 +49 A/G polymorphism is associated with the risk of various cancers, such as breast cancer and cervical cancer." (PMID 33819967, 2021). "Immune checkpoint inhibitors (ICIs) targeting programmed cell death protein-1 (PD-1), programmed cell death ligand 1 (PD-L1), and cytotoxic T-lymphocyte-associated antigen 4 (CTLA-4) can significantly improve the overall survival (OS) in cancer patients." (PMID 34127768, 2021). "Further, our findings offer potential insights into the adverse autoimmunity associated with “CTLA-4 blockade” cancer immunotherapy." (PMID 33483505, 2021). "ICIs block co-inhibitory signals, such as cytotoxic T-lymphocyte-associated protein 4 (CTLA-4) and programmed cell death-1 and programmed death-ligand 1 (PD-1 and PD-L1) axis, to trigger immune responses and eradicate cancer cells." (PMID 33514004, 2021). "Cancer immunotherapies that target the immune checkpoints, such as cytotoxic T lymphocyte-associated antigen 4 (CTLA-4), programmed cell death protein-1 (PD-1), and PD1 ligand-1 (PD-L1), have transformed the therapeutic landscape of a variety of malignancies." (PMID 33658501, 2021). "By blocking programmed death-1 (PD-1)/programmed death-ligand 1 (PD-L1) and cytotoxic T-lymphocyte-associated antigen 4 (CTLA-4), cancer immunotherapy has achieved remarkable therapeutic progress in various kinds of malignances, including HNSCC." (PMID 33687056, 2021). "It has also been reported that ICOS and CTLA4 lead to disturbances of the immune response and thereby indicate an increased risk of cancer." (PMID 33869632, 2021).
cancer (continued). "The expression of programmed death 1 (PD1) / programmed death-ligand 1 (PDL1), cytotoxic T-lymphocyte-associated antigen 4 (CTLA4), and other immune checkpoints, is often significantly increased in malignant tumors and is associated with poor prognosis." (PMID 34012727, 2021). "Cytotoxic T-lymphocyte-associated antigen-4 (CTLA-4), PD-1 protein, and PD-L1 are highly expressed in cancer cells which impedes T-cell recognition and downregulates host immunity." (PMID 34201333, 2021). "One of the major advantages in cancer immunotherapy involves the antibody-mediated blockade of co-inhibitory “checkpoint” molecules, including cytotoxic T lymphocyte-associated protein 4 (CTLA4) and programmed death-1 (PD-1)." (PMID 34600560, 2021). "Immune checkpoints signals are negative regulators of effector T-cells, and the two mainly studied molecules in cancers are Cytotoxic T-Lymphocyte Associated Protein 4 (CTLA-4) and Programmed Cell Death 1 (PD-1)." (PMID 34771694, 2021). "Cancer cells are known to impair antitumor immunity by affecting the cytotoxic T-lymphocyte-associated protein 4 (CTLA-4) and programmed cell death 1 (PD-1) axes with the subsequent downregulation of the T cell effector function." (PMID 33803602, 2021). "The FPscore was significantly associated with GPX4, PD-L1, PD-1, and CTLA4 in many cancers, including HNSCC." (PMID 34512160, 2021). "In recent years, the study of CTLA-4 polymorphisms involved in the tumorigenesis increased rapidly due to interest in genetic susceptibility to cancer." (PMID 33819967, 2021). "Although the use of monoclonal antibodies targeting molecules that inhibit the immune system (CTLA4, PD-L1, PD-1) has been a revolution in the treatment of cancers, they cause IrAEs in 40% -60% of patients with cancer and autoimmune disease." (PMID 34434197, 2021). "Two immune checkpoints in cancer therapy are the programed cell death 1 (PD-1) and cytotoxic T-lymphocyte-associated protein 4 (CTLA-4)." (PMID 33394045, 2021). "Immune checkpoint inhibitors (ICIs) targeting programmed cell death protein 1 (PD-1), its ligand (PD-L1), or cytotoxic T-lymphocyte-associated antigen 4 (CTLA-4) are among the mostly used therapeutics in various cancers in clinical trials and practice." (PMID 33561078, 2021). "Treatment with curcumin also increases the susceptibility of cancer cells to anti-CTLA4 therapy and inhibits tumor growth." (PMID 33466790, 2021). "CTLA4 blockade is associated with enhanced T cell activation and has emerged as a valuable therapeutic tool for cancers." (PMID 34944889, 2021). "Anti-programmed cell death protein-1 (Anti-PD-1)/Anti-programmed cell death ligand-1 (Anti-PD-L1) or Anti-cytotoxic T lymphocyte associated protein 4 (Anti-CTLA-4) antibodies are currently attractive anti-cancer immune checkpoints blockers (ICB)." (PMID 33344447, 2020). "Our results showed that PD-1 and CTLA4 are implicated in cancer immunity, as evidenced by the association between PD-1 and CTLA4 levels and the degree of infiltration of immunocytes in the TIMER and CIBERSORT analyses." (PMID 33072070, 2020). "The concept of the immune checkpoint comes from the first proposal of anti-CTLA-4 (anti-cytotoxic T-lymphocyte-associated protein-4) as cancer immunotherapeutic target antigen in the late 1990s." (PMID 32640575, 2020). "Antibodies against PD-1/programmed death-ligand 1 (PD-L1) or cytotoxic T-lymphocyte-associated protein-4 (CTLA-4) are the most clinically advanced immunotherapy in cancer." (PMID 32351498, 2020). "Our results showed that PD-1 and CTLA4 expression varies across cancer types and that most cancers are characterized by PD-1 and CTLA4 mutations that lead to their abnormal expression, which can serve as a prognostic biomarker." (PMID 33072070, 2020).